VWF (von Willebrand factor)
Diseases named in the same sentence as VWF in open-access papers (continued):
Sharing a sentence is not in itself a finding about the gene and the disease.
malaria (continued). "Plasma VWF:Ag levels were also mildly increased in children with uncomplicated malaria (UM)." (PMID 26766771, 2016). "Notably, the most significant candidates differing between controls and malaria groups were major inflammatory components von Willebrand factor (VWF) and C-reactive protein (CRP)." (PMID 24743550, 2014). "Recent observations have shown that that, in addition to other biomarkers, VWF propeptide is a good marker of cerebral malaria in fatal paediatric malaria and that both VWF and propeptide are good at differentiating between cerebral and mild malaria." (PMID 22125593, 2011). "To further elucidate the mechanism responsible for quantitative and qualitative variations in plasma VWF levels in malaria, we collected plasma samples from a cohort of children with laboratory confirmed severe P. falciparum infection, or full-blown cerebral malaria." (PMID 19300493, 2009). "In African children with P. falciparum malaria, vWF levels were associated with severity, with the highest levels being observed in CM and non-CM severe malaria." (PMID 19450727, 2009). "However, peripheral parasitemia was correlated with vWF levels in both types of malaria." (PMID 40283058, 2025). "Furthermore, plasma VWF∶Ag levels in patients with malaria inversely correlate with platelet count, and we have previously shown that plasma VWF propeptide levels correlate with other established biochemical markers of malaria severity, including plasma lactate." (PMID 19300493, 2009). "Circulating markers of endothelial activation, such as von Willebrand factor (vWF), soluble ICAM-1, VCAM-1, and endothelial microparticles, are significantly increased in severe malaria and possess considerable prognostic value." (PMID 41002937, 2025). "Factors associated with severe malaria that may be affected by hydroxyurea in children with SCA include intracellular adhesion molecule-1 (ICAM-1), vascular cellular adhesion molecule-1 (VCAM-1), von Willebrand factor (VWF), tumor necrosis factor-alpha (TNF-α), and nitric oxide (NO)." (PMID 27339303, 2016). "Furthermore the malaria parasite may be able to modulate the production of VWF through release of an orthologue of Translationally Controlled Tumor Protein (PfTCTP), promoting histamine release from basophils (in vitro), and present in early asymptomatic infection in humans (in vivo)." (PMID 22125593, 2011). "vWF (mediate platelet/PRBCs sequestration) and IL-8 which are co-packed with ANG-2 are also seen elevated in severe malaria." (PMID 22192385, 2011). "vWF levels were also significantly elevated in mild malaria compared to non-malarial controls (non-malarial febrile illness and non-febrile illness) and in cerebral malaria compared to these same controls." (PMID 40283058, 2025). "No increase in P-selectin was seen in knowlesi malaria patients overall compared to controls, and VWF, although increased in knowlesi malaria patients compared to controls, was not increased in severe compared to non-severe disease." (PMID 29872039, 2018). "It has been demonstrated that levels of von Willebrand factor (VWF) are significantly increased in malaria patients compared with non-malarial patients with fever or control subjects." (PMID 22168261, 2011). "Median VWF and propeptide levels were significantly higher in patients with uncomplicated malaria than in children with non-malarial febrile illness of comparable severity, in whom levels were higher than in non-febrile controls." (PMID 22125593, 2011). "Additionally, the highest vWF levels were detected in patients with severe malaria, including cerebral and non-cerebral manifestations." (PMID 40283058, 2025). "Current evidence shows elevated vWF levels in uncomplicated malaria and asymptomatic Plasmodium infections, indicating that increased vWF might not be exclusive to severe cases but could serve as a general marker of Plasmodium infection." (PMID 40283058, 2025).
malaria (continued). "Similarly, vWF levels were significantly elevated in patients with both severe and non-severe malaria compared to controls." (PMID 40283058, 2025). "The observed trends highlight the potential of vWF as a nonspecific marker of infection; however, its role in distinguishing between severe and non-severe malaria remains unclear." (PMID 40283058, 2025). "However, significant rises in vWF levels have also been demonstrated in patients with naturally acquired malaria without the development of any coronary syndromes." (PMID 19958549, 2009).
hemophilia (38 papers, 2011 to 2026). Hemophilia is a genetic disorder characterized by spontaneous hemorrhage or prolonged bleeding due to factor VIII or IX deficiency. "Additional VWF variants were identified in three hemophilia patients." (PMID 31026269, 2019). "In the present study, additional VWF variants were detected in three different hemophilia patients." (PMID 31026269, 2019). "Interestingly, in cases where the underlying F8 genetic variant leads to mild/moderate hemophilia combined with genetic defects in other genes such as VWF (P34, P39) and F11 (P35, P36), bleeding diathesis presented a stronger phenotype compared to the single-gene deficiency." (PMID 33477601, 2021). "Although inhibitor development has been reported in patients treated with VWF concentrates, it is much less commonly observed than inhibitor development in hemophilia." (PMID 40224272, 2025). "When the equilibrium is upset, increased vWF levels and decreased ADAMTS13 activity cause significant platelet and vascular hemophilia factor aggregation formation that can obstruct small blood arteries and cause end-organ ischemia." (PMID 38758904, 2024). "Our study, to the best of our knowledge, is the first time that the VWF:activty/VWF:Ag ratio has been used as a covariate in a linear regression analysis of the rFVIII-Fc half life in hemophilia patients." (PMID 36983209, 2023). "In our laboratory, however, and as supported by VWD diagnosis guidelines from the United Kingdom Haemophilia Doctors Organisation, as approved by the British Committee for Standards in Haematology, we add a fourth assay (the collagen binding (VWF:CB) assay)." (PMID 37601016, 2023). "Three samples were excluded from all analyses except vWF due to the presence of hemophilia (N = 1) or the use of anticoagulants (N = 2)." (PMID 35102534, 2022). "Analyses of factor VIII procoagulant activity (FVIII:C) and the FVIII:C to VWF:Ag ratio (FVIII:C/VWF:Ag ratio) have been investigated as screening bioassays to detect haemophilia carriers." (PMID 35330010, 2022). "The classification was based on the lowest VWF activity measured in the hemophilia center and the severity specified in the medical letter." (PMID 33448867, 2021). "More evidence indicating the important role of VWF in platelet FVIII gene therapy derives from studies of platelet-targeted FIX gene therapy in hemophilia B mice." (PMID 32595633, 2020). "In 2020, it was estimated that 16.5 per 100 000 people in the UK had VWD (type 1: 7.2 per 100 000 people; type 2: 2.5 per 100 000; type 3: 0.3 per 100 000; remaining patients ‘unclassified’ or ‘low von Willebrand factor’ [VWF]) according to the UK National Haemophilia Database (NHD)." (PMID 41071579, 2026). "The clinical implications of low RBC numbers are most associated with the bleeding phenotype of deficient primary hemostasis (ie, VWF in types 1 and 2 and even in type 3 VWD) and platelet function disorders and partially observed in other rarer bleeding disorders, including hemophilia." (PMID 37210074, 2023). "Furthermore, the time course of the VWF−/− soft tissue response to bleeding is qualitatively more like hemophilia mice than WT mice, although quantitatively less great at all time points." (PMID 31594977, 2019). "Using this method, we discovered that the addition of polyP substantially increases VWF activity in plasmas with depleted FVIII, either with chemically removed FVIII or in severe hemophilia patients." (PMID 36430595, 2022). "We report a successful use of ITI consisting of high-dose plasma-derived FVIII rich in vWF and IVIG in a hemophilia patient with high-titer FVIII inhibitor and intron 22 inversion." (PMID 23057781, 2012). "The relationship between vWF:Ag and blood type is known, with non-blood type-O individuals having higher vWF:Ag levels than blood type-O individuals in patients with hemophilia." (PMID 39196490, 2024).
hemophilia (continued). "In the case of underdeveloped nations, the diagnostic evaluation of suspected cases of haemophilia may frequently be hampered by a lack of facilities to measure FVIII, factor IX, FVIII inhibitor, and von Willebrand factor levels." (PMID 37575728, 2023). "In addition to analysis of single genes, combinations were analysed simultaneously, e.g. F8 & F9 (possible carrier relative of deceased haemophilia patient; unknown type); F8, F9, F13A1, F13B and VWF (baby died of bleeding shortly after birth), F8 & VWF (low FVIII:C)." (PMID 27454254, 2016). "Without VWF, the level of platelet-FVIII significantly decreased, and while hemostatic efficacy was still maintained in hemophilia A mice in the absence of inhibitors, it was limited in the presence of anti-FVIII inhibitors." (PMID 32595633, 2020). "If clinicians only order factor assays, and low FVIII:C is identified, then hemophilia may be incorrectly diagnosed in a patient with VWD, since VWF testing was not performed." (PMID 37601016, 2023).
aortic stenosis (34 papers, 2010 to 2025). Aortic valve stenosis is a aortic valve disease caused by the incomplete opening of the aortic valve. "•We found that VWF:RCo/VWF:Ag ratio inversely correlated with large multimer loss in aortic stenosis." (PMID 38268521, 2024). "The narrowed aortic valve in aortic stenosis causes turbulent blood flow and high shear stress, which damages VWF by fragmenting it, particularly the HMWM, reducing its platelet-binding and clot-forming abilities." (PMID 39456826, 2024). "Aortic stenosis causes increased shear stress on the VWF multimers, this is due to the increased speed at which blood traverses through the valve." (PMID 36127959, 2022). "Increased shear stress caused by aortic stenosis results in unfolding of large von Willebrand factor (VWF) multimers and subsequent degradation by the ADAMTS13 metalloproteinase." (PMID 35355968, 2022). "As previously demonstrated, increased shear stress during aortic stenosis (AS) is associated with a loss of the high molecular weight (HMW) of the von Willebrand factor (vWF) due to proteolysis of vWF multimers by the metalloproteinase ADAMTS13." (PMID 34847152, 2021). "Of note, certain cardiac lesions, particularly aortic stenosis, can elongate VWF multimers in the shear field, resulting in proteolytic loss of the highest molecular weight forms, leading to subsequent loss of VWF activity and resultant bleeding." (PMID 34564132, 2021). "In the early 1990s, Warkentin suggested that the association between aortic stenosis and GI bleeding is linked to the deficiency of the largest VWF multimers." (PMID 34322347, 2021). "In obstructive hypertrophic cardiomyopathy, the obstructed left ventricle outflow tract predisposes the proteolysis of HMWM of vWF in a manner similar to aortic stenosis." (PMID 33096906, 2020). "This case highlights the role of severe aortic stenosis and resultant acquired vWF deficiency in complicating decision making in patients with a need for anticoagulation due to high thrombotic risk." (PMID 32601556, 2020). "Increased shear stress, as seen with ventricular assist devices and aortic stenosis, has been reported to cause alterations in the configuration of vWF and reduce the levels of HMW multimers." (PMID 31432279, 2019). "In aortic stenosis, high shear stress through aortic valve induces a loss of high molecular weight von Willebrand factor (vWF) multimers (HMWM), platelet activation and release of platelet granule content." (PMID 29644220, 2018). "Vascular abnormalities, such as aortic stenosis, may cause increased shear rate of the flowing blood that lead to degradation of large VWF multimers in plasma through proteolytic cleavages." (PMID 20920209, 2010). "Gastrointestinal bleeding was initially observed as part of the Heyde syndrome in 1958 (aortic stenosis and gastrointestinal bleeding from angiodysplasia) and is today known to be evoked by the unfolding and loss of high molecular weight multimers of the vWF in AVWS29." (PMID 30976042, 2019). "Of note, the recent paper on AVWS in aortic stenosis patients revealed relatively high levels of VWF:Ag and VWF:RCo, both exceeding 100%, although the latter was statistically significantly lower compared with the control group." (PMID 40918032, 2025). "The primary aim of our study was to investigate the impact of different aortic valve replacement techniques on von Willebrand factor dynamics and postoperative outcomes in patients with severe aortic stenosis." (PMID 39202676, 2024). "Symptoms such as easy bruising, mucosal bleeding, and gastrointestinal bleeding often correlate with the severity of aortic stenosis and VWF abnormalities." (PMID 39456826, 2024). "In aortic stenosis, the pathophysiology of AVWD is complexly linked to the effects of shear stress on VWF caused by the hemodynamic changes associated with a narrowed aortic valve." (PMID 39456826, 2024).
aortic stenosis (continued). "Diagnosis of the syndrome requires a multidisciplinary approach, combining clinical history, endoscopy, imaging studies to detect aortic stenosis, and specific von Willebrand factor tests, such as ristocetin cofactor activity and multimer analysis." (PMID 39803034, 2024). "Shear stress in conditions such as aortic stenosis unfolds the von Willebrand factor multimers, exposing their A2 domain, which allows the enzyme ADAMTS13 to cleave them, reducing the high-molecular-weight multimers essential for platelet adhesion." (PMID 39803034, 2024). "Patients with severe aortic stenosis have been found with levels of HMWM of VWF up to 50% less than the normal value." (PMID 37241186, 2023). "The etiology of angiodysplasia is multifactorial ranging from age-related degeneration of connective tissue and decreased gastric mucosal perfusion in aortic stenosis (AS), and inhibition of von Willebrand factor (vWF) leads to increased angiogenesis." (PMID 37197307, 2023). "A previous study found 42 patients with severe aortic stenosis and concluded that VWF abnormalities are directly related to the severity of aortic stenosis." (PMID 36449459, 2022). "Recently, a series of other potential biomarkers in the circulation have brokered interest, such as for instance von Willebrand Factor (vWF) due to high shear stress in aortic stenosis." (PMID 35721220, 2022). "The current study showed for the first time that valve morphology has an important impact on vWF function in patients with severe aortic stenosis." (PMID 35838799, 2022). "This is because the aortic stenosis exerts high shear stress on large Von Willebrand factor (VWF) multimers leading to their breakdown." (PMID 36127959, 2022). "Studies of acquired von Willebrand syndrome in aortic stenosis and obstructive hypertrophic cardiomyopathy revealed that, despite the clinical manifestation of bleeding, plasma levels of vWF and ristocetin cofactor assay remained at normal values." (PMID 33096906, 2020). "Primary hemostasis, measured by PFA-100 was significantly prolonged; the percentage of HMWM and the collagen-binding activity of vWF were reduced in patients with severe aortic stenosis." (PMID 33096906, 2020). "Etiologies include autoantibodies that directly inhibit the activity of VWF or increase clearance from circulation, shear-stress proteolysis (e.g., aortic stenosis, cardiac devices), and adsorption of VWF onto cells that express the VWF receptor glycoprotein Ib (e.g., Wilm’s tumors)." (PMID 41148947, 2025). "Studies have shown that patients with severe aortic stenosis may have levels of HMWM VWF up to 50% lower than normal values." (PMID 39202676, 2024). "In Heyde syndrome, angiodysplastic vessels create higher shear stress than normal vessels, and the lack of functional VWF in aortic stenosis patients increases their risk of gastrointestinal bleeding." (PMID 39456826, 2024). "Plasma levels and function of vWF is reduced in parallel with severity of aortic stenosis." (PMID 35721220, 2022). "The pathophysiology of AVWS in PH seems to be comparable to that in patients with aortic stenosis and may also result from increased shear stress for large plasma proteins like VWF." (PMID 36452355, 2022). "In aortic stenosis, large-sized VWF multimers are affected; hence generalized bleeding, i.e., not localized to the colon, is less common because small and intermediate-sized VWF multimers remain available for hemostasis." (PMID 34322347, 2021). "In the last years, the loss of HMWM of vWF after CF-LVAD implantation has gained large attention as a presumable cause for bleeding after CF-LVAD implantation, very similar to Heyde syndrome described in patients with severe aortic stenosis." (PMID 28234916, 2017). "VWF:Ag levels were normal in all patients with aortic stenosis and in the control group." (PMID 27841910, 2016). "In cases of known aortic stenosis or repeated bleeding from the angioectasias, testing of VWF multimers might be considered." (PMID 20920209, 2010).
aortic stenosis (continued). "Severe aortic stenosis (AS) or hypertrophic obstructive cardiomyopathy (HOCM) can deplete HMWM of VWF and lead to cryptogenic, gastrointestinal, subcutaneous, and mucosal bleeding." (PMID 36531725, 2022). "Fragmentation of vWF multimers can result from uremia, cirrhosis, or from aortic stenosis (AS)." (PMID 37038581, 2023). "This type is common in patients with cardiac stenotic diseases, especially in aortic stenosis, because of mechanical destruction of the HMW multimers of VWF under high shear stress." (PMID 27841910, 2016). "In patients with aortic stenosis, the shear stress generated by the narrowed aortic valve fragments the high-molecular-weight multimers (HMWM) of von Willebrand factor through the action of the ADAMTS13 enzyme, resulting in their proteolysis and consequently a deficiency of these multimers." (PMID 39803034, 2024). "Additionally, lower pulse pressure, which is observed in aortic stenosis, contributes to the decreased secretion of HMWM of vWF from the endothelium." (PMID 33096906, 2020). "The VWF:Ag and VWF:RCo levels were not statistically different among the patients with aortic stenosis according to degree of stenosis." (PMID 27841910, 2016). "The severity of acquired VWD is related to the aortic stenosis severity, correlating especially with the maximal pressure gradient rather than the aortic valve area, indicating that proteolysis of HMW multimers of VWF is strongly affected by high shear stresses." (PMID 37241186, 2023). "In severe aortic stenosis, HMWM of vWF might decline to approximately 1/2 of the normal levels." (PMID 33096906, 2020). "We examined these parameters in our patient cohort with the following results: None of these patients had a severe aortic stenosis or other pathological findings, which could explain the low vWF:Ac/vWF:Ag ratio preoperatively." (PMID 28234916, 2017). "Similarly to aortic stenosis, high shear stress due to the passage of blood through continuous flow LVAD and biventricular pulsatile VAD results in the cleavage of HMW multimers, resulting in dysfunction vWF and acquired von Willerbrand’s disease." (PMID 27067282, 2016). "No impact of aortic stenosis severity and HMW vWF defect on MPV could be evidenced." (PMID 34847152, 2021).